PRL (prolactin)
Diseases named in the same sentence as PRL in open-access papers (continued):
Sharing a sentence is not in itself a finding about the gene and the disease.
pituitary tumor (continued). "Pathological reviews categorized by immunohistochemistry staining showed GH producing pituitary tumor as the most prevalent result at 55.2%, followed by GH with PRL co-producing tumor at 26.4%, and GH + PRL + FSH/LH producing tumor at 18.4%." (PMID 34795812, 2021). "In this context, nuclear imaging techniques can be useful for predicting responsiveness to SSA also in PRL-secreting pituitary tumors." (PMID 34322092, 2021). "In the treatment of pituitary tumors, DAs are primarily used to treat prolactinomas; and are effective in inhibiting prolactin hypersecretion, reducing tumor size, and restoring gonadal function." (PMID 33754007, 2021). "As we all know, prolactinoma is the most common type of pituitary tumors which is characterized by excessive prolactin (PRL) secretion as the neuroendocrine-related disease." (PMID 34170848, 2021). "Our study also revealed the role of ERα, as a predictor of aggressiveness and prognosis in PRL-secreting pituitary tumors." (PMID 34322092, 2021). "Currently, it is believed that DAR agonists can inhibit the secretion of PRL by binding to D2 DAR expressed on the surface of normal prolactin and pituitary tumor cells." (PMID 34170848, 2021). "Our results are in line with this previous report but interestingly, suggested that galectin-3 can predict the outcome of PRL-secreting pituitary tumors in terms of post-surgical recurrence, response to DA therapy, and disease-free survival." (PMID 34322092, 2021). "Concurrently, there have been similar reports of increased miR182-5p expression in prolactin pituitary tumors and ACTH induced up-regulation of miRNA-182-5p in murine adrenal glands." (PMID 33692756, 2021). "We found a specific inhibitor of TOPK to investigate its effects on the proliferation, migration, apoptosis and PRL secretion of pituitary tumor cells." (PMID 35126305, 2021). "PRL-secreting pituitary tumors are typically larger in males, highly vascularized, more proliferative, and less responsive to DA." (PMID 34322092, 2021). "adenovirus-mediated delivery of tyrosine hydroxylase reduces pituitary growth and circulating prolactin levels in a model of estrogen-induced pituitary tumors in rats." (PMID 32201880, 2020). "Among all subtypes of pituitary tumors, prolactinomas, which are characterized by an overproduction of prolactin (PRL), are the most common." (PMID 32848659, 2020). "Glucocorticoids normally suppress PRL secretion, while it was established that estrogen-induced pituitary tumors in rats, predominantly composed of proliferating lactotropic cells, express low content of glucocorticoid receptors (GR)." (PMID 32188093, 2020). "In rat prolactin- and GH-secreting pituitary tumor cell lines, overexpression of c-terminal-truncated PTTG suppressed prolactin promotor activity, mRNA expression, and hormone levels." (PMID 32012988, 2020). "Malignant prolactinomas are exceedingly rare diseases that are defined as prolactin (PRL)-producing pituitary tumors with cerebrospinal, meningeal, or distant metastasis." (PMID 32760348, 2020). "Histological and immunohistochemical analysis confirmed loss of menin expression in pituitary tumours (n = 4) from C57BL/6 Men1+/- and 129S6/SvEv Men1+/- mice and expression of prolactin, growth hormone and chromogranin A." (PMID 32348957, 2020). "Among all subtypes of pituitary tumors, prolactinomas are the most frequently reported and are commonly characterized by hypersecretion of prolactin (PRL) in the circulating blood." (PMID 33038668, 2020). "Majority of PCs are hormone-secreting tumors, including adrenocorticotropic hormone (ACTH) secreting and prolactin (PRL) secreting tumors, and as such, antibodies for these hormones are used to aid in the diagnosis of pituitary tumor origin." (PMID 30250431, 2018). "Further, two recent articles reported a prognostic impact of Ten-1 overexpression in papillary thyroid carcinoma and prolactin pituitary tumors, respectively." (PMID 28472127, 2017).
pituitary tumor (continued). "In each of these models pituitary tumours occurred in 26–45% of mice by 18 months of age, with prolactin-expressing tumours being the most common." (PMID 26320859, 2016). "The positive pathological staining group, including PRL, FSH, GH, ACTH, TSH, and multiple staining, pituitary tumors, was associated with an increased odds ratio of PA compared with negatively pathological staining tumors (OR: 2.04, 95% CI:1.29~3.23)." (PMID 26407083, 2015). "Recently, a new classification of the five immunohistochemical (IHC) types of pituitary tumors (GH, PRL, ACTH, FSH-LH, and TSH) has been proposed, which introduces a grading that takes the invasion and the proliferation into account." (PMID 26322309, 2015). "Either identified mass is itself a prolactin releasing pituitary tumor or this mass leads to prolactin rise by preventing secretion of prolactin inhibiting factor (dopamine) by compression on hypothalamus or pituitary stalk." (PMID 26246807, 2015). "Prolactin (PRL) secreting tumors are the most common functional neoplasms of the pituitary and are commonly subdivided into microprolactinomas (<10 mm) and macroprolactinomas (≥10 mm) according to their baseline diameter." (PMID 28702224, 2015). "Approximately 60% of pituitary tumors are functionally active, of which prolactinomas [prolactin (PRL) secreting tumors] are the most common subtype." (PMID 26793165, 2015). "GH3 cells, an established estrogen-responsive cell line from rat pituitary tumor cells, secrete PRL and growth hormone (GH)." (PMID 24669252, 2014). "Certain antiestrogenic compounds have been shown to exert a suppressive effect on the cell growth and PRL secretion of normal pituitary cells and pituitary tumor cells." (PMID 24669252, 2014). "In PRL secreting pituitary tumors, the high espression level of D2 receptor explains the good therapeutic response to dopamine agonists, which induces tumor shrinkage." (PMID 25027022, 2014). "This case shows an unusual course of a large prolactinoma following pituitary tumor apoplexy with rapid normalization of prolactin levels but a slower resolution of the pituitary tumor." (PMID 24194992, 2013). "BPA also stimulated calcium influx and prolactin secretion in rat pituitary tumor cells by membrane estrogen receptor α at as low as pM level." (PMID 23083070, 2012). "In vivo, the secretion and synthesis of PRL have been shown to be down-regulated mainly by dopamine D2 receptor agonists and this mechanism is utilized in the treatment of pituitary tumor and other therapeutic applications." (PMID 22152284, 2011). "GH3 cells are somatolactotrophs derived from rat pituitary tumor and produce/secrete PRL and growth hormone (GH)." (PMID 22152284, 2011). "Pituitary tumors secreting prolactin are common in man, and the hormonal regulation of prolactin secretion and gene expression has therefore been extensively studied." (PMID 21532732, 2011). "Approximately 20% of pituitary tumor cells expressed prolactin (PRL), while others expressed the adrenocorticotropic hormone (ACTH)." (PMID 24710044, 2010). "Disproportionate prolactin testing in risperidone-treated patients can ultimately lead to the identification of pituitary tumors that would otherwise remain undetected, because such tumors are usually small, benign, and endocrinologically silent." (PMID 19210771, 2009). "As already mentioned, the prolactin gene is activated by PPARα as demonstrated in a rat pituitary tumor cell line and in reporter gene assays." (PMID 20011657, 2009). "There seems to be an overrepresentation of pituitary tumors in CH patients, and a role of prolactin has been suggested in these cases." (PMID 18651939, 2008). "The first recorded use in a pituitary tumor was in 2006, when an elderly male with recurrent prolactin-secreting pituitary carcinoma achieved stable prolactin levels and a significant reduction in the size of the primary tumor and metastases within 18 months of TMZ therapy." (PMID 40806825, 2025).
pituitary tumor (continued). "Also, the effect of gender (women were not included in this study) on hemodynamic abnormalities in hormonally active PRL-secreting pituitary tumors requires further investigation." (PMID 41244055, 2025). "The aim of this study is to evaluate whether the use of prolactin ratios improves IPSS accuracy in clinical practice at a center of expertise for pituitary tumors, by comparing different prolactin adjustment methods." (PMID 40765079, 2025). "Additionally, ergot alkaloids show potential in controlling prolactin levels, which has implications for treating certain pituitary tumors." (PMID 39849925, 2024). "Prolactin may be raised with pituitary tumours, while thyroid hormones, oestrogens, and androgens need assessment." (PMID 37891382, 2024). "Additionally, patients undergoing investigation of any hypothalamic-pituitary dysfunction (e.g., pituitary tumors, pituitary stalk lesions) should have serum prolactin measured." (PMID 38578472, 2024). "Most cases present with pituitary tumors secreting GH and prolactin." (PMID 37908565, 2023). "Further research is necessary to determine the impact of serum prolactin on neural recovery after injury–which might inform therapeutic approaches for central nervous system pathologies other than pituitary tumors." (PMID 35921360, 2022). "Although older guidelines suggest higher cut-offs (>250 ng/mL) to diagnosis prolactinomas, newer studies highlight the ratio of prolactin to tumor volume and lower levels, between 55-94 ng/mL, may also suggest prolactin secreting pituitary tumors." (PMID 36246929, 2022). "However, prolactinomas are among the most radio-resistant pituitary tumours, and normoprolactinaemia is reached in only one-third of the cases, with the effects on PRL decline delayed by several years." (PMID 35683457, 2022). "Moreover, the effects of the patients’ sex (females were not evaluated in this study) on hemodynamic dysfunction in active PRL-secreting pituitary tumors requires further study." (PMID 36558529, 2022). "However, this study described a monocentric series of patients affected by PRL-secreting pituitary tumors naïve to DA therapy and underwent first line treatment with pituitary surgery." (PMID 34322092, 2021). "TOPK inhibitor HI-TOPK-032 could suppress the proliferation & migration and induce apoptosis of pituitary tumor cells in vitro, and reduce PRL secretion and tumor growth in vivo." (PMID 35126305, 2021). "Initial therapy of choice for PRL-PAs consists, usually, of dopamine agonists, while other pituitary tumors are addressed by transsphenoidal surgery and subsequent pharmacological therapy with somatostatin analogs (SSAs) and dopamine agonists, or radiotherapy for resistant or metastatic tumors." (PMID 34439107, 2021). "The cell experiment showed that two compounds could inhibit the proliferation and PRL secretion of MMQ cells (pituitary tumor cells)." (PMID 34170848, 2021). "Prolactin-secreting pituitary tumors (PRL-omas) are generally benign neoplasia." (PMID 34322092, 2021). "Finally, removal of PRL-producing pituitary tumors or treatment with drugs that inhibit PRL release reverse sexual dysfunctions." (PMID 33398068, 2021). "A specific disease model – compression of retinofugal fibers by large prolactin-secreting pituitary tumors (i.e., prolactinomas) offers a “natural experiment” with which to observe the potential mechanisms through which prolactin exerts a neuroprotective role in the injured human brain." (PMID 34307410, 2021). "By inhibiting TOPK in vivo and in vitro, we explored the effect of HI-TOPK-032 on the proliferation, apoptosis, cell cycle distribution and migration of pituitary tumor cells, and investigated it’s effect on PRL secretion and tumor growth in prolactinoma model rats." (PMID 35126305, 2021).
pituitary tumor (continued). "As further evidence of the importance of the pituitary clock, circadian expression of pituitary POMC and PRL mRNA was observed in cultured murine pituitary tumor cell lines (AtT20, GH3 and GH4C1), and their expression correlated to the circadian proteins (PER-2 for POMC, and CLOCK for PRL)." (PMID 32272677, 2020). "The patients may also have other signs and symptoms depending on the aetiology of the PRL excess (e.g., mass effects, in case of a pituitary tumour (headaches, visual disturbances, hypopituitarism))." (PMID 31847209, 2019). "In contrast, the lack of tumor-generating ability of human pituitary TSCs in mice was reported in another study, in which stem-like cells were successfully isolated from 38 of 56 pituitary tumors of different types (GH-, GH/PRL-, and ACTH-secreting tumors and NFPTs)." (PMID 31708878, 2019). "TENM1 is related to tumor metastasis in prolactin pituitary tumors." (PMID 28678795, 2017). "Moreover, the observed shift to a pronounced nuclear localization in ISCC confirms a previous observation in aggressive-invasive subtypes of pituitary tumors (prolactin) that suggest a crucial role for PTTG1 during squamous carcinogenesis." (PMID 28073359, 2017). "Finally, large prolactin-secreting pituitary tumours often (even in 78 % of patients) lead to the development of hypopituitarism; the gonadal and somatotropic axes being the most frequently affected." (PMID 25239203, 2015). "Consequently, it would be interesting to explore the role of TGFB1 in PRL pituitary tumor aggressiveness and malignancy." (PMID 26322309, 2015). "Similar effects of FLNA on DRD2 regulation were also found in PRL-secreting pituitary tumors." (PMID 26733942, 2015). "In order to identify candidate miRNAs involved in progression to aggressiveness and malignancy, we used criteria based on the main differences between aggressive and non-aggressive PRL pituitary tumors, which are linked to proliferation." (PMID 26322309, 2015). "Higher prolactin levels usually suggest the presence of a pituitary tumor (prolactinoma)." (PMID 26246807, 2015). "Prolactin secreting adenomas are the most frequent type among pituitary tumors." (PMID 25505910, 2014). "The most common functional pituitary tumors hypersecrete prolactin (PRL) (40–45%)." (PMID 25291362, 2014). "These pituitary tumors stains appeared positive for PRL but also for LH in 29-34 days old mouse." (PMID 25870702, 2014). "This therapy is effective in more than 85% of patients with prolactin-secreting pituitary tumors." (PMID 25505910, 2014). "Pituitary tumors that produce GH and PRL have long being recognized to derive from mammosomatotrophs; they are the most common type of mixed adenomas and they may co-express α sub-unit glycoprotein." (PMID 25870702, 2014). "PitNETs immunopositive for more than one pituitary hormone (including associations like GH/PRL, but also unusual IHC combinations like GH/ACTH) presented FS cells in a statistically significant percentage, suggesting their involvement in the selection of pituitary tumor lineages." (PMID 40643539, 2025). "By inhibiting the activity of TOPK in vitro, it was found that the inhibition of TOPK could reduce proliferation and migration of pituitary tumor cells, induce apoptosis and cell cycle arrest, and decrease PRL production at the gene, protein and secretion levels." (PMID 35126305, 2021). "Some studies have shown that Hyper-PRL may be mainly due to pituitary tumors." (PMID 35098010, 2021). "Moreover, it has been reported in TSH-, PRL-, and GH-secreting pituitary tumors." (PMID 31835737, 2019).
pituitary tumor (continued). "The differential diagnosis of a large pituitary tumour with moderately elevated prolactin (PRL) concentrations is sometimes difficult, and prolonged treatment with a dopamine agonist may be inappropriate when the diagnosis of a prolactinoma is not sufficiently well substantiated." (PMID 29632566, 2015). "Among the 60 pituitary tumors, 10 were hormonally active, showing positive expression for ACTH, hGH, or PRL." (PMID 40002278, 2025). "D2 receptor agonists are highly effective in controlling prolactin secretion and tumor size in prolactinomas, and beneficial actions of D2 agonists have also been reported in GH- and ACTH-secreting pituitary tumors." (PMID 40565361, 2025). "Functioning pituitary tumors possess the ability to secrete one or more pituitary hormones (ACTH, PRL, growth hormone (GH), thyroid-stimulating hormone (TSH), follicle-stimulating hormone (FSH), luteinizing hormone (LH))." (PMID 39553112, 2024). "An increased Gal-3 expression in PRL− and ACTH-PitNETs has been described, but why and how it is involved in pituitary tumor progression is still unclear." (PMID 37958702, 2023). "The pituitary gland is an important endocrine organ, and the development of PA is accompanied by endocrine changes, and serum PRL, IGF-1, and GH determinations are the main basis for the diagnosis of pituitary tumors." (PMID 35356252, 2022). "In GH-secreting pituitary tumor cells, the activity of FLNA is influenced by cAMP/PKA-mediated phosphorylation at amino acid residue Ser2152, as observed in PRL- and ACTH-secreting cells." (PMID 37435454, 2022). "Non-functional pituitary tumors were the most common pituitary tumors, 24 and 17, respectively, followed by PRL, GH, and ACTH pituitary tumors." (PMID 33192965, 2020). "A rat pituitary tumor cell line, GH3, was first described as a homogenous clonal cell line that secretes Gh and, later, was shown to also secrete prolactin (Prl)." (PMID 27706259, 2016). "Although long-acting DA and SS analogs are currently used in the treatment of prolactin (PRL)- and growth hormone (GH)-secreting pituitary tumors, respectively, clinical practice indicates a great variability in the frequency and entity of favorable responses." (PMID 26733942, 2015). "An ESE survey of 171 patients with aggressive pituitary tumors and carcinomas identified six patients, five with ACTH-secreting and one with a silent prolactin-staining adenoma, who were treated with either dual or single agent ICIs for 2 to 14 months as second-line therapy." (PMID 40806825, 2025). "Pituitary tumors described in MAS are almost exclusively GH and/or prolactin-secreting adenomas." (PMID 40078582, 2025). "Thus, the first step for advancing the knowledge of patients with GH/PRL PitNETs is to reach a consensus on the definition of GH/PRL PitNETs; in this regard, the latest WHO pituitary tumor classification seems to be the most appropriate way." (PMID 37762304, 2023). "Imaging evidence for pituitary tumor in this patient lacked, and corresponding treatment for elevated prolactin and growth hormone levels was not given." (PMID 37795364, 2023). "This trend was significant when assessing PRL levels and RNFL for non-secreting pituitary tumors with moderately elevated PRL levels (NS+) due to stalk effect." (PMID 35921360, 2022). "In summary, this study demonstrates attenuation of injury to the retina during anterior visual pathway injury with moderately elevated prolactin levels in non-secreting pituitary tumor patients." (PMID 35921360, 2022). "The pituitary tumor from patient 8 stained positive for reticulin, GH, prolactin (data not shown), and NF1." (PMID 35456261, 2022). "Of the non-secreting pituitary tumors, 12 were identified to have stalk effect, and 40 patients had normal levels of serum prolactin." (PMID 35921360, 2022).